DBF4B (DBF4B-CDC7 kinase regulatory subunit)
Description:
Regulatory subunit for CDC7 which activates its kinase activity thereby playing a central role in DNA replication and cell proliferation. Required for progression of S and M phases. The complex CDC7-DBF4B selectively phosphorylates MCM2 subunit at 'Ser-40' and then is involved in regulating the initiation of DNA replication during cell cycle.
Synonyms: ASKL1; DRF1; FLJ13087; chifb; ZDBF1B
Tractability: PROTAC: ubiquitination databases record sites on it.
Gene: Protein-coding gene on chromosome 17 (44,708,608 to 44,752,264, forward strand). Ensembl gene ENSG00000161692.
Subcellular location: Nucleus
Subcellular location (Human Protein Atlas): Nucleoplasm; Vesicles
Gene Ontology:
Molecular function: protein binding; protein kinase activator activity; protein kinase binding; protein serine/threonine kinase activator activity; nucleic acid binding; zinc ion binding
Biological process: positive regulation of cell population proliferation; positive regulation of G2/M transition of mitotic cell cycle; positive regulation of nuclear cell cycle DNA replication; regulation of cell cycle phase transition
Cellular component: chromatin; cytoplasm; nucleoplasm; nucleus; Dbf4-dependent protein kinase complex
Genetic constraint (gnomAD): Loss-of-function variants: 39 observed, 50.79 expected, observed/expected ratio (o/e) 0.77, 90% interval 0.59 to 1. The upper end of that interval is the gene's LOEUF score, 1, which puts it in group 4 of 6, group 1 being the genes least tolerant of losing a copy. Missense variants: 663 observed, 785.94 expected, observed/expected ratio (o/e) 0.84, 90% interval 0.79 to 0.9. Synonymous variants: 250 observed, 296.08 expected, observed/expected ratio (o/e) 0.84, 90% interval 0.76 to 0.94.
Homologues: Orthologues: chimpanzee DBF4B (99% identical), macaque DBF4B (61% identical), pig DBF4B (56% identical), tropical clawed frog dbf4b (23% identical), zebrafish dbf4b (20% identical), dog DBF4B (19% identical), Drosophila melanogaster chif (16% identical). Paralogues in human: DBF4 (20% identical).
Diseases named in the same sentence as DBF4B in open-access papers:
DBF4B is named in the same sentence as 10 diseases in open-access papers, as found by Europe PMC text mining. Sharing a sentence is not in itself a finding about the gene and the disease. The quoted sentences say what the papers report.
breast carcinoma (2 papers, 2020 to 2022). "Three (LDHA, DBF4B, and MASP1) were predicted to be targeted by miRNA identified as differentially expressed in breast cancer tissues of cases compared to controls in the study of Du and collaborators or Ohzawa and collaborators." (PMID 36627894, 2022).
colon cancer (2 papers, 2020 to 2022). "Recently SRSF1 is found to regulate the alternative splicing of the serine-threonine kinase DBF4B that plays a vital role in promoting tumorigenesis in colon cancer cells." (PMID 35027535, 2022). "DBF4B-FL is required for colon cancer cell proliferation and maintenance of genomic stability." (PMID 33352742, 2020).
breast tumors (1 paper, 2020). "Low BRCA1 expression in cells along with BRCA1 inactivation in breast tumors is associated with reduced expression of CCNL2, DBF4B, and TRIM45." (PMID 32290274, 2020). "Given the functional implications of BRCA1 inactivation on the translation of ADAT2, CCNL2, DBF4B, and TRIM45, we wondered whether the levels of these proteins were correlated to BRCA1 status in breast tumors." (PMID 32290274, 2020).
colorectal cancer (1 paper, 2025). A primary or metastatic malignant neoplasm that affects the colon or rectum. "Recent research has indicated the involvement of DBF4B in colorectal cancer progression." (PMID 40535802, 2025).
hepatocellular carcinoma (1 paper, 2025). A malignant tumor that arises from hepatocytes. "Regarding OS, higher DBF4B expression was associated with worse prognosis in subgroups such as Age > 60, BMI ≤ 25, Race: Asian, Gender: male, Residual tumor: R0, Histological type: Hepatocellular carcinoma, Pathological stage: Stage III, Tumor state: With tumor, Pathological T stage: T3." (PMID 40535802, 2025). "In terms of DSS, higher DBF4B expression was associated with worse prognosis in subgroups such as Age > 60, BMI ≤ 25, Race: Asian, Gender: male, Residual tumor: R0, Histological type: Hepatocellular carcinoma, Pathological stage: Stage III, Tumor state: With tumor, Pathological T stage: T3." (PMID 40535802, 2025). "Regarding PFI, higher DBF4B expression was associated with worse prognosis in subgroups such as Age > 60, BMI ≤ 25, Race: Asian, Gender: male, Residual tumor: R0, Histological type: Hepatocellular carcinoma, Tumor state: With tumor, Vascular invasion: Yes Albumin (g/dl): >= 3.5." (PMID 40535802, 2025). "We specifically concentrated on hepatocellular carcinoma, revealing that DBF4B could serve as an independent prognostic factor in this cancer type." (PMID 40535802, 2025). "Additionally, we investigated the correlation between DBF4B expression in hepatocellular carcinoma and the prognosis of clinical subgroups (OS, DSS, PFI)." (PMID 40535802, 2025). "Conducting IHC on hepatocellular carcinomas, we verified the expression of DBF4B in both cancer and normal tissues, revealing higher DBF4B expression in LIHC compared to normal tissues." (PMID 40535802, 2025).
melanoma (1 paper, 2025). A malignant, usually aggressive tumor composed of atypical, neoplastic melanocytes. "Furthermore, we examined the expression of DBF4B mutation counts in pan-cancer, revealing that endometrial, colorectal, and melanoma have higher mutation counts compared to other cancers." (PMID 40535802, 2025).
retinoblastoma (1 paper, 2025). A malignant tumor that originates in the nuclear layer of the retina. "KEGG analysis revealed five pathways positively associated with DBF4B expression: retinoblastoma gene cancer, resolution of sister chromatid, CD22-mediated BCR regulation, kinesins, and the role of phospholipids in phagocytosis." (PMID 40535802, 2025).
Skin Cutaneous Melanoma (1 paper, 2025). "It is evident that among all cancers, patients with Skin Cutaneous Melanoma have the highest frequency of DBF4B alterations (>5%), primarily characterized by mutations and amplifications." (PMID 40535802, 2025).
tumor (4 papers, 2020 to 2025). "We observed differential expression of DBF4B in several subgroups of clinical features, including pathological stage, tumor status, race, weight, histological type, histological grading, AFP, and vascular invasion." (PMID 40535802, 2025). "Conversely, a positive correlation was observed in 2 cancers, suggesting an intricate interaction between DBF4B, tumor cells, and immune cells." (PMID 40535802, 2025). "We utilized the UALCAN database to investigate the methylation levels of the DBF4B promoter in tumor tissues compared to normal tissues in pan-cancer." (PMID 40535802, 2025). "Conversely, DBF4B expression was higher in tumor tissues than in normal tissues in BRCA, COAD, LUSC, PAAD, and SARC." (PMID 40535802, 2025). "Both DBF4B full-length (DBF4B-FL) variant and SRSF1 promote tumor cell proliferation and tumor growth while the DBF4B-short (DBF4B-S) variant does not exhibit a similar function." (PMID 34330892, 2021). "This implies a robust correlation between DBF4B expression and immune infiltration of tumor cells." (PMID 40535802, 2025). "Furthermore, our analysis showed that DBF4B expression in liver hepatocellular carcinoma (LIHC) was associated with a variety of factors, including age, gender, race, height, weight, body mass index (BMI), presence of residual tumor, and tumor status." (PMID 40535802, 2025). "Therefore, BRCA1 may control DNA replication and S phase progression in response to DNA damage, two hallmarks of its tumor suppressor activity, through at least in part positive regulation of DBF4B translation." (PMID 32290274, 2020). "Significantly different expressions of DBF4B were observed in various clinical features of LIHC, including pathological stage, tumor status, ethnicity, body weight, histological type, histological grade, alpha-fetoprotein, and vascular infiltration." (PMID 40535802, 2025). "Firstly, we selected several genes related to tumor metastasis through the NCBI database and literature, including SRA1, DBF4 zinc finger B (DBF4B), ZNFX1 antisense RNA 1 (ZFAS1), colorectal neoplasia differentially expressed (CRNDE), endoplasmic reticulum lectin (OS9), and others." (PMID 34011971, 2021).
cancer (2 papers, 2020 to 2025). A tumor composed of atypical neoplastic, often pleomorphic cells that invade other tissues. "Utilizing multiple publicly available databases enables us to conduct a comprehensive analysis of cancer and investigate the role of DBF4B in cancer diagnosis, methylation, drug sensitivity, mutation, immune infiltration, prognosis, and other factors." (PMID 40535802, 2025). "We delved into the genetic alterations of DBF4B across various cancers and identified genetic mutations in DBF4B in most tumors, with the highest frequency observed in SKCM." (PMID 40535802, 2025). "Moreover, a positive correlation was observed between DBF4B expression and the expression of RNA modification-related genes (m1A, m5C, m6A) in most cancers, indicating a strong association." (PMID 40535802, 2025). "In conclusion, DBF4B may be a key molecular biomarker for pan-cancer immunology and prognosis and an independent prognostic risk factor for LIHC." (PMID 40535802, 2025). "Additionally, we identified 17 cancers where DBF4B exhibited a higher diagnostic value." (PMID 40535802, 2025). "To complement the normal tissue data, we combined the TCGA and GTEx databases to explore DBF4B expression in pan-cancer." (PMID 40535802, 2025). "We obtained data from the TISIDB database on the correlation between molecular subtypes and immune subtypes of DBF4B in pan-cancers." (PMID 40535802, 2025). "Our study affirmed that DBF4B expression was significantly up-regulated in 16 cancers and down-regulated in 1 carcinoma type, as evident from the TCGA and GTEx databases." (PMID 40535802, 2025). "We conducted pan-cancer bioinformatics analysis of DBF4B, covering differential expression, diagnosis, prognosis, methylation, and pharmacological sensitivity through multiple databases." (PMID 40535802, 2025). "These explorations confirmed that DBF4B predominantly functions as an oncogene across various tumors, contributing to cancer formation and progression." (PMID 40535802, 2025). "We obtained scatter plots showing the correlation between DBF4B expression and 33 cancers using the ESTIMATE algorithm to derive immune scores, stromal scores, and ESTIMATE scores." (PMID 40535802, 2025). "We used the Univariate Cox analysis to explore the three indicators of OS, DSS, and PFI, reflecting the relationship between DBF4B expression in pan-cancer and cancer prognosis." (PMID 40535802, 2025). "Our results showed that DBF4B was significantly differentially expressed in most cancer types as well as in cancers with different molecular and immune subtypes, and DBF4B was also significantly correlated with the prognosis of a subset of cancers." (PMID 40535802, 2025). "This suggests that DBF4B may influence the prognosis of patients with various types of cancer through methylation." (PMID 40535802, 2025). "Scatter plots were used to depict DBF4B expression in pan-cancer." (PMID 40535802, 2025). "Additionally, we observed that DBF4B closely correlated with 13 molecular subtypes and 9 immunosuppressive subtypes of cancers." (PMID 40535802, 2025). "This establishes a groundwork for further exploration into the mechanistic role of DBF4B in cancer." (PMID 40535802, 2025). "The analysis of DBF4B expression with immunomodulation-related genes and immune checkpoint-related genes in dicated a strong correlation in most cancers, particularly with genes involved in chemokine, receptor, MHC, Immunoinhibitor, and Immunostimulator pathways." (PMID 40535802, 2025). "This suggests a potential role of DBF4B in cancer inhibition in these instances." (PMID 40535802, 2025). "We applied TIMER2.0 to explore the expression of DBF4B in pan-cancer." (PMID 40535802, 2025). "Our study comprehensively investigated DBF4B across various dimensions at the pan-cancer level, encompassing differential expression, diagnosis, prognosis, gene mutation, molecular and immunosubtyping, immune infiltration, methylation, drug sensitivity, and enrichment analysis." (PMID 40535802, 2025).
cancer (continued). "However, the regulatory mechanisms of DBF4B in cancer warrant further exploration." (PMID 40535802, 2025). "Furthermore, we observed a strong correlation between DBF4B expression and RNA-regulated genes across multiple cancers, implying that DBF4B may contribute to tumorigenesis via the RNA methylation pathway, thereby promoting cancer development." (PMID 40535802, 2025). "We focused on ADAT2, CCNL2, DBF4B, and TRIM45 mRNAs that played key roles in cancer biology to demonstrate that alteration of their translational efficiency occurred via a BRCA1-dependent mechanism in cultured cells and in patient tumors." (PMID 32290274, 2020). "In the context of tumors, DBF4B regulation by shear of SRSF1 has been reported, promoting cancer." (PMID 40535802, 2025). "Additionally, DBF4B showed a positive correlation with HMGB1, BTN3A1, and VEGFA across various cancers." (PMID 40535802, 2025). "Our analysis revealed a negative correlation between the expression of DBF4B and stromal and immune scores in 19 cancers." (PMID 40535802, 2025). "However, our study has not yet addressed the molecular mechanism of DBF4B in cancer, and further exploration of the mechanism of DBF4B action in cancer is needed in the future." (PMID 40535802, 2025).